CSF3R (colony stimulating factor 3 receptor)
Diseases named in the same sentence as CSF3R in open-access papers (continued):
Sharing a sentence is not in itself a finding about the gene and the disease.
sarcoma (2 papers, 2019 to 2022). A usually aggressive malignant neoplasm of the soft tissue or bone. "The increased sarcoma development observed in Csf3r−/− neutrophil-deficient mice was associated with lower levels of IL-12p70 and IFNγ." (PMID 31257026, 2019). "We found increased frequencies of iNKT, MAIT, and DNTαβ cells in Csf3r−/− sarcomas, but only the polarization of DNTαβ cells was altered in neutropenic mice." (PMID 31257026, 2019). "A trend toward a skewed UTCαβ polarization was also observed in the spleen of Csf3r−/− tumor-bearing mice, although to a minor degree compared to sarcoma-infiltrating cells." (PMID 31257026, 2019). "γδ T cells from Csf3r−/− sarcomas showed increased Rorγt expression, while Eomes and T-bet expression was not altered in this cell type." (PMID 31257026, 2019). "Adoptive transfer of bone marrow Csf3r+/+ neutrophils (purity >98.5%) into Csf3r−/− sarcoma-bearing mice was sufficient to completely rescue tumor growth to the level of Csf3r+/+ controls." (PMID 31257026, 2019). "The Ifng mRNA levels detected in UTCαβ isolated from Csf3r+/+ sarcomas were comparable to that expressed by CD8+ and γδ T cells, indicating the significance of UTCαβ-derived IFNγ in the TME." (PMID 31257026, 2019). "Neutrophil adoptive transfer restored the expression of IL-12p70 and IFNγ in the TME of sarcoma-bearing Csf3r−/− mice." (PMID 31257026, 2019). "Clusters 1–4 represented more than 75% of total UTCαβ and were differentially enriched in Csf3r+/+ and Csf3r−/− sarcomas." (PMID 31257026, 2019). "Correlation analysis performed on the whole transcriptome highlighted the existence of two main functionally distinct cluster groups, which mirrored the respective composition of UTCαβ subsets in Csf3r+/+ and Csf3r−/− sarcomas." (PMID 31257026, 2019). "In Csf3r+/+ sarcoma-bearing mice, TANs displayed an activated phenotype, characterized by increased expression of CD11b and CD54 and decreased expression of CD62L, compared to peripheral blood neutrophils." (PMID 31257026, 2019). "Gene set variation analysis (GSVA) performed on differentially expressed genes for each cluster showed the enrichment of IFNγ signaling and IL-12 signaling mediated by STAT4 in clusters enriched in Csf3r+/+ sarcomas (clusters 2 and 4), in line with data obtained by flow cytometry." (PMID 31257026, 2019). "We validated these findings by flow cytometry on sarcoma-infiltrating Csf3r+/+ T cells." (PMID 31257026, 2019). "However, cohousing did not affect sarcoma susceptibility, excluding that a potential dysbiosis associated with Csf3r deficiency was involved in the observed phenotype." (PMID 31257026, 2019).
ulcerative colitis (2 papers, 2025). An inflammatory bowel disease involving the mucosal surface of the large intestine and rectum. "CSF3R expression was positively correlated with IL22 and IL23 expression in patients with ulcerative colitis, and patients with higher CSF3R expression were also found to have enriched epithelial repair and regeneration gene profiles." (PMID 40906170, 2025).
viral infection (2 papers, 2019 to 2024). "Additionally, the CSF1 signal, also originating from dendritic cells, was received by macrophages and dendritic cells via CSF3R and CSF1R, playing a role in differentiation and activation following viral infection." (PMID 38743760, 2024).
aneurysm (1 paper, 2009). Bulging or ballooning in an area of an artery secondary to arterial wall weakening. "Genes that can be considered as markers for the following cell types were upregulated in aneurysms: neutrophils (Csf3r); T lymphocytes (Cd3d) and B lymphocytes (Blnk, Cd72, various immunoglobulin genes); and monocyte/macrophages (Cd14, Cd68)." (PMID 19580648, 2009).
atherosclerosis (1 paper, 2024). A disease characterized by the build-up of fatty material and calcium deposition in the arterial wall resulting in partial or complete occlusion of the arterial lumen. "A study has reported the correlation of CSF3R and Atherosclerosis." (PMID 38598492, 2024).
bone marrow failure syndrome (1 paper, 2019). "We detected CSF3R mutations in CN patients with different genetic backgrounds, but not in patients with other types of bone marrow failure syndromes chronically treated with G-CSF (e.g., Shwachman-Diamond Syndrome)." (PMID 30891028, 2019).
breast tumours (1 paper, 2024). "For example, CSF3R, among the "other targets," is 338-fold more expressed in blood cells than in breast tumours (adjusted p-value < 1 x 10−350)." (PMID 38306344, 2024).
depression (1 paper, 2023). "It has been showed that CSF3R is a cytokine that controls neutrophil expansion and differentiation, and can serve as a biomarker for neuromodulation; FPR2 knockdown may maintain hippocampal homeostasis by preventing depression-related neuronal damage." (PMID 37649561, 2023).
discoid lupus erythematosus (1 paper, 2024). A chronic, autoimmune skin condition that manifests with a red, scaling rash, most often found on the face, ears, and scalp; these lesions often lead to permanent scarring and dyspigmentation. "Among the uniquely expressed genes in each disease, we observed significantly expressed IFNG in Discoid Lupus Erythematosus, TRAT1 in Epitheliotropic Lymphoma, and CXCL8 and CSF3R in pemphigus affected dogs." (PMID 39911479, 2024).
dyskeratosis congenita (1 paper, 2020). Dyskeratosis congenita (DC) is a rare ectodermal dysplasia that often presents with the classic triad of nail dysplasia, skin pigmentary changes, and oral leukoplakia associated with a high risk of bone marrow failure (BMF) and cancer.
E. coli infection (1 paper, 2024). "Furthermore, qRT‒PCR showed that E. coli infection and LPS stimulation decreased the CSF3R mRNA level in WT neutrophils." (PMID 38114747, 2024).
gastric tumors (1 paper, 2022). "To shed light on myeloid populations present in gastric tumors, we re-clustered the 10,546 myeloid cells in our dataset and identified fifteen subclusters which were subsequently determined to be either macrophages (CD68, CD14), dendritic cells (FLT3, FCER1A), or neutrophils (CSF3R)." (PMID 36550535, 2022).
graft versus host disease (1 paper, 2025). An immune system disorder that occurs after allogeneic hematopoietic stem cell transplant and is a reaction of donor immune cells against host tissues. "For instance, in graft-versus-host disease, SOCS1 regulates the inflammatory response by suppressing T-cell activation via inhibition of the CSF3R/JAK2/STAT3 signaling pathway." (PMID 40918404, 2025).
Granuloma (1 paper, 2025). A compact, organized collection of mature mononuclear phagocytes, which may be but is not necessarily accompanied by accessory features such as necrosis. "A diverse array of innate immune cells, including mast cells (MC) (cluster 20: HDC, CPA3, KIT), dendritic cells (DC) (cluster 23: CLNK, WDFY4, FLT3), neutrophils (FCGR3B, FFAR2, CSF3R), and macrophages (CD68, CD163, C1QA/B/C), was also present in these granulomas." (PMID 40772762, 2025).
hepatoblastoma (1 paper, 2021). Hepatoblastoma (HB) is a malignant hepatic tumor and is the most common pediatric liver cancer. "CSF3R hypermethylation is related to cisplatin resistance in hepatoblastoma patients." (PMID 33371790, 2021).
hereditary neutrophilia (1 paper, 2017). A leukocyte disease characterized by autosomal dominant inheritance of lifelong, persistent elevated neutrophil counts primarily consisting of segmented neutrophils that has material basis in heterozygous mutation in the CSF3R gene on chromosome 1p34. "By contrast, CSF3R P733T mutations detected in CMML patients were completely different from CSF3R mutation types described in patients with CNL, SCN and hereditary neutrophilia, which may be a potential diagnostic marker, particularly for wt SRSF2 CMML patients." (PMID 28209919, 2017).
Kawasaki disease (1 paper, 2026). A rare inflammatory disease characterized by an acute febrile, systemic, self-limiting, medium-vessel vasculitis primarily affecting children. "Five biomarkers-CD177, Matrix Metallopeptidase 9, Nuclear Factor Erythroid 2, Colony Stimulating Factor 3 Receptor, and Suppressor Of Cytokine Signaling 3-were consistently upregulated in Kawasaki disease and showed high diagnostic accuracy (area under the curve >0.94 in both datasets)." (PMID 41743406, 2026).
lung carcinoma (1 paper, 2019). "A recent report further showed that monocytes expressing S100A8, S100A9, and colony stimulating factor 3 receptor (CSF3R) were found in both human and mouse lung cancer tissue." (PMID 31651369, 2019).
lung squamous cell carcinoma (1 paper, 2025). "The m7G immune-related genes FGA, CSF3R, and ORM1 increase the survival risk in patients with lung squamous cell carcinoma, whereas NTS exerts a protective effect." (PMID 40098956, 2025).
medulloblastoma (1 paper, 2023). A malignant, invasive embryonal neoplasm arising from the cerebellum. "A crucial aspect of identifying CSF3R gene activity in medulloblastomas is understanding the effects of oncologic treatment on the disease." (PMID 36982406, 2023). "All these findings suggest that, even if there is not a direct effect of the CSF3R gene on the mortality of patients with medulloblastoma, other factors, such as treatment, may influence this outcome." (PMID 36982406, 2023).
metabolic syndrome (1 paper, 2023). A cluster of metabolic risk factors for CARDIOVASCULAR DISEASES and TYPE 2 DIABETES MELLITUS. "Seven metabolic syndrome-related genes (CSF3R, TMEM132A, STAB1, VIM, DUOXA1, PILRB, and SLC2A4) were used to construct risk equations." (PMID 37033267, 2023).
metastasis (1 paper, 2020). The spread or migration of cancer cells from one part of the body (where they first appeared) to another. "Moreover, expression of individual genes in this panel, including IL18RAP, CXCL11, FCER1G, CSF3R and IL2RG were strongly linked to distant metastasis, lymph node metastasis, tumor stage, clinical stage or pathologic grade." (PMID 33049716, 2020).
Myelodysplasia (1 paper, 2025). Clonal hematopoietic stem cell disorders characterized by dysplasia (ineffective production) in one or more hematopoietic cell lineages, leading to anemia and cytopenia.
myelofibrosis (1 paper, 2025). A partial or complete replacement of the bone marrow stroma by fibrous tissue. "One patient with CSF3R mutations was observed in MDS, 2 cases in CMML and 4 in other myeloproliferative neoplasia (1 CNL, 1 hypereosinophilia, 1 secondary myelofibrosis MF post-PV and 1 primary MF), accounting for frequencies of 1.1%, 7.4% and 6.7% respectively." (PMID 39907800, 2025).
nonalcoholic fatty liver disease (1 paper, 2024). "In addition, the CSF3/CSF3R axis is involved in lipid metabolism and promotes the development of nonalcoholic fatty liver disease and AS29,30." (PMID 38503760, 2024).
pemphigus (1 paper, 2024). Pemphigus is a group of rare autoimmune diseases that cause blistering of the skin and mucous membranes (mouth, nose, throat, eyes, and genitals).This conditioncan occur at any age, but often strikes people in middle or older age. "We validated significant upregulation of IFNG in DLE (p ~ 0.01), and a significant upregulation of CXCL8 and CSF3R in pemphigus." (PMID 39911479, 2024). "Specifically, we noted a unique expression of IFNG in DLE (p = 0.0213), a unique expression of TRAT1 and FOXO3A in EL patients (p < 0.0001 and p < 0.0001), and CXCL8 and CSF3R in pemphigus patients (p = 0.0002 and p = 0.0016)." (PMID 39911479, 2024). "Furthermore, treatments like B-raf inhibitors that inhibit MAPK, a pathway vital to CSF3R upregulation, can be investigated and applied to pemphigus patients." (PMID 39911479, 2024).
polyneuropathy (1 paper, 2024). A disease or disorder affecting more than one nerve. "The changes in Fkpb5 and Csf3r found in all three models may reflect common neuroinflammatory mechanisms in opioid tolerance and polyneuropathy, which could be of significance when treating NP with opioids." (PMID 38933596, 2024).
preeclampsia (1 paper, 2015). Preeclampsia is a hypertensive disorder of pregnancy that is characterized by new-onset hypertension with proteinuria presenting after 20 weeks of gestation, and depending on mild or severe forms may initially present with severe headache, visual disturbances, and hyperreflexia. "RT-qPCR confirmed aberrant expression of genes involved in inflammation and stress response (TLR4 and TLR9) and also genes involved in host defense (PRDX5, MIF, CD74, NFE2L1, and CSF3R), suggesting that preeclampsia sera suppress the TLR4/9-dependent excess oxidative stress in adipose tissue." (PMID 26089598, 2015).
psoriasis (1 paper, 2025). An autoimmune condition characterized by red, well-delineated plaques with silvery scales that are usually on the extensor surfaces and scalp. "The differential expression analysis identified several upregulated differentially expressed genes, including OSM, CXCL8, TREM1, CXCL1, CSF3R, BCL2A1 and CXCL2, in relapsed psoriasis skin compared with baseline lesional skin." (PMID 40181552, 2025).
seminoma (1 paper, 2024). A radiosensitive malignant germ cell tumor found in the testis (especially undescended), and extragonadal sites (anterior mediastinum and pineal gland). "Another pan-cancer TCGA-based study found that colony-stimulating factor 3 receptor (CSF3R) is up-regulated in TGCT, and its promoter’s methylation level was found to be lower in non-seminomas compared with seminomas." (PMID 38791003, 2024).
undifferentiated pleomorphic sarcoma (1 paper, 2019). An undifferentiated soft tissue sarcoma characterized by the presence of a pleomorphic malignant cellular infiltrate. "In selected human tumors, including undifferentiated pleomorphic sarcoma, CSF3R expression, a neutrophil signature and neutrophil infiltration were associated with a type 1 immune response and better clinical outcome." (PMID 31257026, 2019).
tumor (63 papers, 1997 to 2025). "Patients were divided into IDH-mutated and IDH wild-type tumor groups, and then patients within each group were also classified according to high or low CSF3R expression levels." (PMID 38474265, 2024). "These correlations suggest that higher CSF3R expression is a characteristic of multiple gene signatures associated with pro-tumor immune environments in CRC patients." (PMID 33606788, 2021). "The Cancer Genome Atlas (TCGA) data analysis revealed that CSF3 and CSF3R are associated with a large number of changes in the tumor microenvironment of CRC." (PMID 33606788, 2021). "To identify the signaling pathways specifically activated on cancer-associated UTCαβ, we compared the transcriptome of tumor-associated Csf3r+/+ UTCαβ with γδ T cells and conventional CD4+ and CD8+ T cells and found 190 differentially expressed genes." (PMID 31257026, 2019). "In this study, we found that the low-risk group had significantly higher CD79A and CSF3R expression than the high-risk group, which suggests that tumor immunity might be related to somatic mutations." (PMID 33371790, 2021). "Currently, it is unknown whether CSF3 and CSF3R expression are associated with patient demographics, stage at presentation, location of tumor, mutational status, CMS subtype, or distinct patterns of immune infiltrates." (PMID 33606788, 2021). "We hypothesized that CSF3 and CSF3R would be associated with pro-tumor immune signatures and pathways." (PMID 33606788, 2021). "These co-mutations likely contribute to the phenotypic heterogeneity and clinical variability observed in these CSF3R-driven neoplasms." (PMID 40806796, 2025). "We observed increased expression of receptors such as CXCR2, CXCR1, and CSF3R in TAN that have been reported to be crucial for neutrophil recruitment to the tumor parenchyma." (PMID 38358826, 2024). "CSF3R (GCSFR) expression is also more abundant in tumor tissue, specifically in subtypes CMS1, CMS3, and CMS4." (PMID 36911097, 2023). "Current knowledge about the CSF3R gene is limited, and many other questions remain unanswered regarding its role in tumor recurrence and patient survival." (PMID 36982406, 2023). "Understanding CSF3R gene expression is, therefore, crucial to understanding each tumor type’s oncogenesis and, eventually, seeking ways to block it." (PMID 36982406, 2023). "Here, we show that expression of CSF3 and CSF3R are associated with CMS1 and CMS4 classifications, pro-tumor gene scores, and regulation of both innate and adaptive cells in the TME." (PMID 33606788, 2021). "We examined correlations of CSF3 and CSF3R expression with patient demographics, tumor stage and consensus molecular subtype classification." (PMID 33606788, 2021). "This notion is supported by genes such as the checkpoint kinase 2 (CHEK2) and tuberin, which have been described as tumor suppressors; or CSF3R which has been described as an oncogene." (PMID 27150584, 2016). "As previously discussed, the constitutive activation of signaling pathways like JAK-STAT and SRC/TNK2 in CSF3R-altered neoplasms presents opportunities for targeted interventions with documented efficacy using JAK inhibitors such as ruxolitinib in these neoplasms." (PMID 40806796, 2025). "Monocytes and neutrophils recruited by these cytokines and signalling though the G-CSF receptor (Csf3r) may limit the anti-tumour immune response." (PMID 37605008, 2023). "The role that CSF3 and CSF3R play in the evolution of the CRC tumor microenvironment may offer a potential therapeutic target and should be further explored." (PMID 33606788, 2021). "Moreover, differentiated CD103+ cDC1s express only low amounts of Csf3r mRNA, suggesting they are refractory to tumor-produced G-CSF within the TME." (PMID 31947933, 2020). "CD103+ cDC1s express relatively low amounts of Lifr and Csf3r mRNAs versus other immune subsets such as pDCs or granulocytes, respectively, suggesting they may be refractory tumor-produced LIF or G-CSF." (PMID 31947933, 2020).